CD9 (CD9 molecule)
Diseases named in the same sentence as CD9 in open-access papers (continued):
Sharing a sentence is not in itself a finding about the gene and the disease.
keloid (3 papers, 2021 to 2024). An irregularly shaped, elevated mark on the skin caused by deposits of excessive amounts of collagen during wound healing. "For evaluating the possible connection between hypoxia and CD9 on HSFs and HKFs (Human keloid fibroblasts), Western blots were performed after cultured cells were then exposed to hypoxic conditions (2% O2)." (PMID 39333849, 2024). "Additionally, we discovered that hypoxia upregulates CD9 expression in human keloid fibroblasts, so further research is necessary to explore if tetraspanins mediate scar formation under hypoxic conditions, given the fact that TGF-β1/Smad pathway promotes scars." (PMID 39333849, 2024). "The increased levels of markers such as CD9, CD38 and CD39 in keloid and perilesional tissue potentially indicated that also these cells had started to differentiate." (PMID 34502327, 2021). "Therefore, we flow-sorted keloid fibroblasts that were CD90+ and CD266+/CD9− or CD90+ other cells (other fibroblasts)." (PMID 34140509, 2021).
liver cancer (3 papers, 2017 to 2022). An epithelial or non-epithelial malignant neoplasm that arises from the liver. "In the next experiments, we assessed the protein biomarker of sEV with FITC-conjugated mAbs specific to CD63 and CD9 derived from fresh liver cancer tissue, frozen liver cancer tissue and cultured liver cancer tissue sections." (PMID 34550537, 2022).
multiple sclerosis (3 papers, 2013 to 2022). A progressive autoimmune disorder affecting the central nervous system resulting in demyelination. "Modulation of CD9 expression is even under consideration in auto-immune diseases, such as multiple sclerosis, in which blocking CD9 in vitro strongly enhances the blood-brain barrier function and reduces the migration of monocytes across brain endothelial cell monolayers." (PMID 30356731, 2018).
nasopharyngeal carcinoma (3 papers, 2021 to 2025). A carcinoma arising from the nasopharyngeal epithelium. "Furthermore, we found that the core genes of the nasopharyngeal carcinoma radiosensitivity signature (NPC-RSS), namely SMARCA2, DMC1, CD9, PSG4, and KNG1, had significant correlations with previously published genes related to radiosensitization." (PMID 40530955, 2025).
non-small cell lung carcinoma (3 papers, 2011 to 2013). A group of at least three distinct histological types of lung cancer, including non-small cell squamous cell carcinoma, adenocarcinoma, and large cell carcinoma. "We stably expressed CD9 in HT1080 cells at mRNA and cell surface levels similarly to the endogenous expression of CD9 in other cancerous cell lines including colon and non-small cell lung cancer." (PMID 23840773, 2013).
periodontal disease (3 papers, 2020 to 2025). "The role of various subpopulations of sEVs from different tetraspanin proteins (CD63+, CD9+, CD81+ subtypes) in periodontal disease has not been widely investigated and requires further elucidation." (PMID 33670900, 2021).
prostate tumor (3 papers, 2014 to 2015). "Western blot analysis data demonstrated exceptional enrichment of exosomal markers (TSG 101, CD9) and epithelial cell adhesion molecule (EpCAM), as well as moderately enriched prostate tumor-marker PSMA in exosomes when compared to relatively stable α-tubulin levels in cells and exosomes." (PMID 24424840, 2014). "Both CD9 translocations and IGSF8 deletions are observed in 2–3% of prostate tumors." (PMID 26036626, 2015).
renal cell carcinoma (3 papers, 2021 to 2025). "Other less prevalent malignant kidney tumors included a renal cell carcinoma (RC), which showed a CD271+ CD81+ EpCAM+ CD71+ CD117+ phenotype in the absence of CD9, CD10, CD58, CD90, CD105, and GD2, and a clear cell sarcoma, which expressed CD271+ and GD2+ without EpCAM." (PMID 34638431, 2021).
skin infection (3 papers, 2016 to 2020). An inflammatory process affecting the skin, caused by bacteria, viruses, parasites, or fungi. "Synthetic peptides of tetraspanin, CD9 prevent Staphylococccus aureus skin and wound infections to cultured keratinocytes and human skin infection model." (PMID 33087788, 2020). "Synthetic peptides derived from a keratinocyte-expressed tetraspanin, CD9, were tested for anti-adhesive properties and at low nanomolar concentrations were shown to inhibit bacterial adhesion to cultured keratinocytes and to be effective in a tissue engineered model of human skin infection." (PMID 27467693, 2016).
squamous cell carcinoma (3 papers, 2004 to 2019). A carcinoma arising from squamous epithelial cells. "The purpose of this study is to determine the predictive value of CD9 in squamous cell carcinoma (SCC) of the head and neck." (PMID 14735195, 2004). "In the same way, an increase of the expression of proteins, such as ECM1, CD9, and CD44 has been reported in EVs derived from squamous cell carcinoma cells upon mesenchymal transformation." (PMID 31453379, 2019).
acute promyelocytic leukemia (2 papers, 2020 to 2025). An aggressive form of acute myeloid leukemia (AML), characterized by arrest of leukocyte differentiation at the promyelocyte stage, due to a specific chromosomal translocation t(15;17) in myeloid cells. "The manuscript is well written with description of a very informative topic of expression pattern of CD9 in acute promyelocytic leukemia (APL)." (PMID 33236622, 2020).
allergic disease (2 papers, 2014 to 2024). An immune response that occurs following re-exposure to an innocuous antigen, and that requires the presence of existing antibodies against that antigen. "In T cells, several tetraspanin proteins, including CD9, CD81 and CD82 are reported to associate with CD4 or CD8 and enhance T cell effector functions, while CD81 negatively modulates FcεRI-mediated degranulation in mast cells and suppress IgE-dependent allergic reactions." (PMID 24832104, 2014).
atopic dermatitis (2 papers, 2023 to 2026). "The expression of the tetraspanins such as CD9, CD37, CD53, CD63, CD81, and CD82 on FcεRIpos skin dendritic cells (DCs) from atopic dermatitis patients is significantly higher when compared to skin DCs of not allergic healthy individuals." (PMID 36672710, 2023).
B cell lymphoma (2 papers, 2019 to 2021). "A study examining several B cell lymphoma cell lines found no CD9 expression and variable CD63 and CD81 levels." (PMID 33513976, 2021).
chondrosarcoma (2 papers, 2021 to 2024). A malignant cartilaginous matrix-producing mesenchymal neoplasm arising from the bone and soft tissue. "In turn, tumor cells from the only chondrosarcoma (CDS) analyzed were also positive for GD2 and CD9, in addition to CD81 and CD90, and they lacked CD10, CD58, nuMyoD1, numyogenin, CD57, and CD99 expression." (PMID 34638431, 2021).
colorectal adenocarcinoma (2 papers, 2021 to 2024). The most common type of colorectal carcinoma. "Finally, we also found that halting the cell cycle with dinaciclib in two cancer cell lines, SH-SY5Y and HT29 (human colorectal adenocarcinoma-derived), dominantly suppresses the release of CD9+ sEVs, suggesting the broad relevance of our biological findings." (PMID 39562573, 2024).
colorectal tumor (2 papers, 2010 to 2023). "In a model of colorectal tumor, we explored Tspan8 interacting molecules by mass spectrometry and found that compared to CD9, Tspan8 specifically recruits the endothelin converting enzyme ECE1 to tetraspanin-enriched microdomains and positively modulates its enzymatic activity." (PMID 37835445, 2023). "Similarly, expression of motility-related protein (MRP1/CD9) is highly repressed in metastases compared with primary colorectal tumours, and anti-MRP1/CD9 antibodies abrogate tumour cell migration." (PMID 20087350, 2010).
cutaneous melanoma (2 papers, 2022). A primary melanoma arising from atypical melanocytes in the skin. "Our aim was to analyse CD9 expression in melanocytic nevi and primary cutaneous melanomas through immunohistochemistry and immunofluorescence approaches to determine its correlation with invasiveness and metastatic potential." (PMID 35563166, 2022). "Currently, little is known about CD9 prognostic value in cutaneous melanoma." (PMID 35563166, 2022).
depression (2 papers, 2022 to 2024). "In the present study, the KOA patients with elevated CD41+/CD63+/CD9+ sEVs reported greater BDI scores, supporting the known association between platelet activation and depression." (PMID 38254142, 2024). "The observed connection between depression and CD41+/CD63+/CD9+ sEVs in KOA suggests that the potential of EV subpopulations as biomarkers of mental status warrants further investigation." (PMID 38254142, 2024).
glaucoma (2 papers, 2020 to 2022). Increased pressure in the eyeball due to obstruction of the outflow of aqueous humor. "Exosome particle count in each CD 63, CD 81, and CD9 spot was significantly greater in PEX glaucoma than in controls in total, CD 63, CD9, syntenin, and scattering(all p < 0.003)." (PMID 35896586, 2022). "CD9 is down‐regulated in glaucoma, overexpression of CD9 can active integrin α4 (ITGA4), PI3K and Akt, which lead to the decreased apoptosis and attenuate glaucoma." (PMID 31680442, 2020). "Overexpression of CD9 can decrease the apoptosis activity of glaucoma cells, which was benefit for glaucoma treatment." (PMID 31680442, 2020). "CD9 is down‐regulated in glaucoma, overexpression of CD9 can active integrin α4 (ITGA4), PI3K and Akt, which lead to the decreased apoptosis of TM cell and maintained the TM cell identity." (PMID 31680442, 2020). "In glaucoma, overexpression of CD9 can activate expression of ITGA4, phosphorylated PI3K, and Akt, which lead to the inactivation of apoptosis." (PMID 31680442, 2020). "All these results showed that CD9/ITGA4/PI3K‐Akt axis can mediate apoptosis activity to attenuate glaucoma." (PMID 31680442, 2020). "Next, we want to investigate the molecular mechanism of CD9 in regulating glaucoma." (PMID 31680442, 2020). "Furthermore, rescue experiment validated that CD9/ITGA4/PI3K‐Akt axis mediated TM cell apoptosis in glaucoma." (PMID 31680442, 2020). "Importantly, we identified and demonstrated that CD9 played key roles in glaucoma by biological experiment." (PMID 31680442, 2020). "Thus, whether CD9 can participate in glaucoma via ITGA4 and downstream pathways is proposed by our study." (PMID 31680442, 2020). "Thus, we thought that CD9 might be a candidate regulator in glaucoma." (PMID 31680442, 2020). "Interestingly, in our filter results, we found 2 genes (CD9 and ITGA4) had a great potential to function in glaucoma." (PMID 31680442, 2020). "Interestingly, we found 8 genes (FN1, THBS1, EPHB2, FGF2, DAB2, CD9, PLAUR and ITGA4) were crucial, suggesting that these genes might function as key factors in the pathogenesis of glaucoma." (PMID 31680442, 2020).
glomerular disease (2 papers, 2019 to 2024). "As we observed that CD9 expression in PEC correlated with PEC activation in experimental CGN and FSGS, and that CD9 depletion was associated with decreased ITGB1 levels, we analyzed CD9 expression in combination with CD44 and ITGB1 in human glomerulopathies." (PMID 31341160, 2019). "We found that CD9 closely colocalized with ITGB1 during human extracapillary glomerulopathies such as ANCA-associated CGN and FSGS, but not in non-proliferative glomerulonephritides or in normal kidney." (PMID 31341160, 2019). "Key observations in rodent models could be reproduced in human glomerulopathies, suggesting a role for CD9 also in human disease." (PMID 31341160, 2019).
HCMV infection (2 papers, 2017 to 2018). "Furthermore, we analyzed the involvement of specific tetraspanin domains, the LEL and the C-terminus, in HPV and HCMV infection by using recombinant peptides or proteins comprising these domains of CD9, CD63, CD81 and CD151 tetraspanins." (PMID 30279342, 2018). "CD81 is a tetraspanin, like CD151 and CD9 that were also downregulated upon HCMV infection." (PMID 29121670, 2017). "It has been shown that CD9, CD81 and CD151 were downregulated during HCMV entry and that cellular depletion of CD9, CD63 and CD151 reduced HCMV infection." (PMID 30279342, 2018). "Peptides comprising the C-terminal CD9 and CD81 peptide had only minor effects on HCMV infection." (PMID 30279342, 2018). "Therefore it is likely that CD9 benefits HPV and HCMV infection by organization of virus entry platforms (TEMs) or the modulation of the activity or accessibility of interaction partners like proteases as it was proposed for entry of MERS viruses." (PMID 30279342, 2018). "In this study we compared the importance of tetraspanins CD9, CD63, CD81 and CD151 in infections by human papilloma- and cytomegalovirus and investigated whether peptides of functional tetraspanin domains could be used as inhibitors of HPV and HCMV infection." (PMID 30279342, 2018). "This discrepancy of the consequences of cellular depletion versus treatment of cells with CD9 C-terminal peptides might imply that CD9 affects HPV and HCMV infection via a function that does not involve C-terminal dependent cytoplasmic interactions." (PMID 30279342, 2018).
lung diseases (2 papers, 2020 to 2022). "Potentially the therapeutic targeting of dysregulated Cd151- and Cd9-signaling may contribute to improved and more effective therapy for pulmonary diseases." (PMID 33424923, 2020).
meningioma (2 papers, 2013 to 2025). A generally slow growing tumor attached to the dura mater. "Statistically significant differences were also observedfor TNC+ EVs (FC = 27.2, p < 0.01)and the subpopulation TNC+/CD9+ (FC = 34.5, p < 0.01) when compared to meningioma patients." (PMID 40056466, 2025). "In this regard, TiMa of both −22/22q− and cytogenetically complex meningiomas also showed higher expression of both the CD44 and CD9 adhesion molecules vs diploid cases." (PMID 24098347, 2013).
pancreatitis (2 papers, 2018 to 2025). Inflammation of the pancreas. "The Western blot analysis showed that our EVs from the clinical control, pancreatitis, and PDAC patients were positive for CD63 and CD9." (PMID 40003965, 2025).
parasitic infections (2 papers, 2020 to 2025). "Although CD9 has been described to modulate viral and bacterial infections, the role of tetraspanins in the pathogenesis of parasitic infections remains unclear." (PMID 41019078, 2025).
rhabdomyosarcoma (2 papers, 2013 to 2015). A rare aggressive malignant mesenchymal neoplasm arising from skeletal muscle. "Indeed, human rhabdomyosarcoma-derived myoblasts overexpressing CD9 formed approximately fourfold more syncytia than control cells." (PMID 25890097, 2015).
sarcopenia (2 papers, 2018 to 2025). Progressive decline in muscle mass due to aging which results in decreased functional capacity of muscles. "Notably, Lin and colleagues employed the SAM-P8 senescence-accelerated mouse model and, via integrated transcriptomic and proteomic profiling, identified CD9 as a pivotal gene strongly associated with sarcopenia." (PMID 41568005, 2025). "The pathophysiological relevance of CD9 in human sarcopenia remains unproven, and the specificity, efficacy, and long-term safety of the shortlisted compounds must be systematically evaluated across multiple animal strains." (PMID 41568005, 2025). "Gene set enrichment analysis (GSEA) further suggests that CD9 contributes to the onset and progression of sarcopenia by modulating mitochondrial biogenesis and oxidative phosphorylation." (PMID 41568005, 2025). "Future investigations should focus on delineating the precise molecular mechanisms by which CD9 governs mitochondrial function, and on assessing its evolutionary conservation in human sarcopenia as well as its potential as a novel biomarker or therapeutic target." (PMID 41568005, 2025). "Therefore, the osteopenia and sarcopenia seen in DKO mice cannot simply be attributed to the spill-over effect from the lung, but must involve disorganization of the fusion machinery after CD9/CD81 depletion." (PMID 29572511, 2018).
staphylococcal infection (2 papers, 2023 to 2025). An infection caused by Staphylococcus. "We provide insights into the mechanisms that underlie staphylococcal infection of host cells, linking two known adhesion pathways together through CD9 for the first time." (PMID 37486132, 2023). "In total, 12 human proteins were enriched during meningococcal infection, compared to one during staphylococcal infection, demonstrating different host factor requirements during CD9-mediated bacterial adherence." (PMID 41105917, 2025). "Here, we define the role of CD9 in staphylococcal adherence and uptake, observing that CD9 coordinates syndecan-1, fibronectin, and β1 integrins to allow efficient staphylococcal infection." (PMID 37486132, 2023).
steatosis (2 papers, 2024). Increased lipid within the cytoplasm of cells. "In particular, as recently reported, SerpinB3 was able to influence the hepatic levels of Galectin 3, CD9 and TREM2, typical markers of NAMs, a population of hepatic macrophages emerging in progressive NAFLD-NASH and strictly associated with severity of steatosis, inflammation as well as fibrosis." (PMID 38307387, 2024). "Our study clarified a vital role of CD9 in hepatic lipid accumulation and steatosis." (PMID 38837628, 2024).
thyroid cancer (2 papers, 2011 to 2022). "In our study, the incubation of NTHY cells with EVs isolated from two thyroid cancer cell lines, TPC-1 and BcPAP, stimulated the expression of CD9, suggesting a possible protumorigenic effect." (PMID 35328683, 2022). "Investigations performed on AUF1-depleted thyroid cancer cell lines revealed a cross-link between AUF1 and CD9, CD82, S100A4 and ENO1." (PMID 21835052, 2011). "We demonstrated that down-regulation of CD9, CD82 and RKIP may reflect an increased in vivo metastatic potential of thyroid cancer cells." (PMID 21835052, 2011).
transmissible spongiform encephalopathy (2 papers, 2021 to 2022). "CD9 is upregulated in the mouse and human brains infected with transmissible spongiform encephalopathy." (PMID 35682902, 2022).
Zika virus infection (2 papers, 2021 to 2025). "Altogether, these results suggest that Zika virus infection and transmissive capabilities are compromised due to overexpression of CD9, CD63, and CD81." (PMID 34190582, 2021). "Our results showed that ALIX, CD9 (exosomal biogenesis), SOD-1, and CAT (regulation of oxidative stress) had decreased protein expression levels during ZIKV infection, in contrast to the mock-infected cells." (PMID 40572291, 2025).
acute kidney injury (1 paper, 2024). Sudden and sustained deterioration of the kidney function characterized by decreased glomerular filtration rate, increased serum creatinine or oliguria. "A Western blot analysis of uEVs showed increased abundances of uEV-specific tetraspanin CD9 and tetraspanin CD63 in patients with acute kidney injury on the first postoperative day (p < 0.05 by Mann–Whitney test)." (PMID 39334890, 2024). "The discovery cohort showed elevated CD9, CD63, and uEV-AQP2 levels in urine from recipients with acute kidney injury compared to immediate allograft function." (PMID 39334890, 2024). "On day 29 post-transplant, the CD9 and CD63 abundances were not different between patients with acute kidney injury and immediate allograft function." (PMID 39334890, 2024).
age-related macular degeneration (1 paper, 2022). Age-related loss of vision in the central portion of the retina (macula), secondary to retinal degeneration. "In retinal vascular diseases such as diabetic retinopathy and age-related macular degeneration, TGFβ2, CD9, and CTGF are elevated, inducing choroidal and retinal micro vessel development." (PMID 35456925, 2022).
AIDS (1 paper, 2023). A syndrome resulting from the acquired deficiency of cellular immunity caused by the human immunodeficiency virus (HIV). "EVs isolated from serum samples of HIV+ controls and HIV+ pre-AIDS-NHL cohort participants were characterized by quantifying the expression of EV specific markers, CD9 and TSG101, to verify their identity as EVs." (PMID 37809067, 2023).